ENSG00000285868 (Novel protein)
Gene: Protein-coding gene on chromosome 5 (157,341,596 to 157,460,100, reverse strand). Ensembl gene ENSG00000285868.
Genetic constraint (gnomAD): Loss-of-function variants: 3 observed, 9.65 expected, observed/expected ratio (o/e) 0.31, 90% interval 0.14 to 0.8. That is too few expected variants to judge how well the gene tolerates losing a copy. Missense variants: 279 observed, 301.86 expected, observed/expected ratio (o/e) 0.92, 90% interval 0.84 to 1.02. Synonymous variants: 114 observed, 121.61 expected, observed/expected ratio (o/e) 0.94, 90% interval 0.8 to 1.1.